MDM4 (MDM4 regulator of p53)
Diseases named in the same sentence as MDM4 in open-access papers (continued):
Sharing a sentence is not in itself a finding about the gene and the disease.
tumor (continued). "Recently, a study reported on five patients experiencing hyper-progression who had NGS performed on pretreatment tumor tissue, and it confirmed CNAs in MDM2/MDM4, epidermal growth factor receptor (EGFR), and several genes located on 11q13 associated with hyper-progression." (PMID 32903763, 2020). "For example, among MB-SHH models, the SJMBSHH-16-02525 PDOX did not disclose the MDM4 amplification detected in the patient tumor sample." (PMID 32519082, 2020). "Of note, estrogens mediate sexual dimorphism in the sensitivity conferred by Mdm4 to DNA damage but not in its tumor-promoting function." (PMID 31547268, 2019). "Overall, these data indicate that Mdm4 accelerates DNA-damage induced tumor formation without being affected by mouse gender." (PMID 31547268, 2019). "Since MCF7 express a fraction of MDM4 into the nucleus —a feature frequently occurring in human tumor cells —it was not possible to quantitatively analyze MDM4 re-localization by immunofluorescence upon estradiol treatment in these cells." (PMID 31547268, 2019). "Noteworthy, Mdm4 enhances chemo- and radio-sensitivity in male but not in female animals, whereas its tumor-promoting activity is not affected by mouse gender." (PMID 31547268, 2019). "Only the primary tumor and its derived gliomaspheres exhibited EGFR and MDM4 amplification." (PMID 29416795, 2018). "Similarly, when we examined other tumor types with DIEXF amplification, we found significant overlap with MDM4 amplification." (PMID 29262616, 2017). "Our results suggest that splicing of Mdm4 does not promote tumor development and does not cooperate with other oncogenic insults to alter tumor latency or aggressiveness." (PMID 28460439, 2017). "Although we cannot comment on expression or protein levels of either MDM4 or MAGE in this patient’s tumor, the co-amplification significance of multiple MAGE genes and MDM4 may merit further exploration in this tumor type." (PMID 28056866, 2017). "Overall, 36.6% (123/336) of tumor sections and 15.2% (5/33) of the corresponding adjacent normal gastric tissue sections (P = 0.009) were classified as the MDM4 high expression." (PMID 27626496, 2016).
tumor (continued). "Once the logFC values are considered, however, in BRCA the negative correlations are observed between MDM4 and tumor cell metabolism such as cellular glucuronidation (GO:0052695), lipid catabolic process (GO:0044242), and alcohol dehydrogenase (NADP+) activity (GO:0008106)." (PMID 38281029, 2024). "Notably, our findings highlight seven genes (FAM30A, MDM4, POU2AF1, SYNE2, TNFRSF13C, TPTEP2, VAMP1) presenting positive correlations with ESR2 expression patterns in all tumor types with high ESR2 expression as a positive prognostic factor with regard to OS or DFS." (PMID 39201394, 2024). "MDM4-211 and MDM4-Alt1 expression were absent in all tumor samples." (PMID 39273363, 2024). "One tumor with PLAGL2 amplification (#A113—excluded from the core DNA methylation cohort due to QC issues, but with a clear signal for ET, PLAGL), harbored additional focal high-level amplifications of the MDM4 oncogene on chromosome 1q32.1 and the MYCN oncogene on chromosome 2p24.3." (PMID 36437415, 2023). "Concerning copy number aberrations (CNAs), the top amplified genes in the samples from the primary tumor were ERBB2 (6/19, 32%), AURKA, PPM1D (4/19, 21%), and FGFR1 (3/19, 16%), while in the metastatic samples ERBB2 (7/17, 41%), CDK12, FGFR1 (4/17, 24%), and AURKA, MDM4, MYC (3/17, 18%)." (PMID 36717329, 2023). "In contrast, AKT3 and MDM4 amplifications were the only driver CNV events found in RAI-refractory PTCs (both in 4.5%, 3/66 of cases; p = 0.076; Fisher’s Exact Test), and only a single RAI-avid tumor (PTC-501) exhibited multiple driver CNV events (p = 1.000; Fisher’s Exact Test)." (PMID 35326735, 2022). "This last hypothesis is supported by the evidence that tumor growth is not significantly affected by the overexpression of Mdm4." (PMID 31547268, 2019). "However, cases where either MDM4 or DIEXF amplification occurred independent of each other were also present in all tumor types examined." (PMID 29262616, 2017). "In our analysis, although we sampled only a fraction of the tumor, the similar cell age estimated for MDM4+/EGFR+ and MDM4+/PDGFRA+ clones suggested that neither of these clones gained selective advantage during tumor growth." (PMID 38724668, 2025). "Finally, we investigated genes displaying similar expression patterns as ESR2 in tumor tissues, identifying potential co-expressed genes that may exert a synergistic effect on clinical outcomes, with significant results, including the expression of ACIN1, SYNE2, TNFRSF13C, and MDM4." (PMID 39201394, 2024). "However, this may also not necessarily mean that MDM4 is not a target for tumor growth inhibition." (PMID 34384473, 2021).
tumor (continued). "Taken together, our phylogenetic analysis suggests that GBM subclones with amplification of EGFR and MDM4 were eliminated by surgery and RT/TMZ treatment, while a population of tumor cells without the amplification remained viable." (PMID 29416795, 2018). "However, the gene‐level integrated analysis revealed heterogeneity in expression, copy number variation and methylation status of MDM4, RRAGC, HERC2, BIRC3 and TSC2 genes within and across individual tumours, suggesting that they may not be ideal biomarkers for PDAC." (PMID 35061935, 2022).
hematologic malignancies (2 papers, 2017 to 2024). "AMG-232 has also shown activity against both MDM2 and MDM4 in preclinical studies and is currently being evaluated in clinical trials for hematologic malignancies." (PMID 39538363, 2024). "Additionally, combination therapies with other agents may enhance the efficacy of MDM2 and MDM4 inhibitors and improve outcomes for patients with hematologic malignancies." (PMID 39538363, 2024).
infection (2 papers, 2014 to 2022). The state of being infected such as from the introduction of a foreign agent such as serum, vaccine, antigenic substance or organism. "To test the efficiency of the employed gRNA, we transduced HEK293T cells with a GFP-reporter construct expressing Cas9 and MDM4-gRNA and analyzed the targeted genomic locus by Sanger sequencing 5 days after infection." (PMID 35269477, 2022).
cardiovascular diseases (1 paper, 2025). "Interestingly, MDM4 is found to participate in various cardiovascular diseases, where its dysregulation correlates with cardiomyocyte cell death and impaired cardiac function." (PMID 40813720, 2025).
degenerative diseases (1 paper, 2024). "Venkatesh’s findings showed that inhibiting MDM4 could be beneficial in preventing degenerative diseases involving ferroptosis." (PMID 38536018, 2024).
metabolic disease (1 paper, 2021). A congenital disorder (due to inherited enzyme abnormality) or acquired (due to failure of a metabolically important organ) disorder resulting from an abnormal metabolic process. "Evaluating whether some of these polymorphisms also correlate with metabolic phenotypes may unravel new interesting connections between MDM2/MDM4 and metabolic diseases." (PMID 33406607, 2021).
MDM4 also shares sentences with these, for which no sentence is quoted: soft tissue sarcoma (5 papers); esophageal squamous cell carcinoma (3); malignant glioma (3); adenocarcinoma (2); angiosarcoma (2); breast adenocarcinoma (2); cholangiocarcinoma (2); Clear Cell Renal Cell Carcinoma (2); metastatic melanoma (2); multiple myeloma (2); Parkinson disease (2); Pheochromocytoma and Paraganglioma (2); prostate adenocarcinoma (2); small cell lung carcinoma (2); Type 1 diabetes (2); actinic keratosis (1); acute lymphoid leukemia (1); Ad- (1); adenosquamous carcinoma (1); Allergy (1); asthma (1); Astrocytoma (1); atherosclerosis (1); autoimmune enteropathy (1); autoimmune hepatitis (1); cardia cancer (1); cardiac sarcomas (1); cardiomyopathy (1); cervical squamous cell carcinoma (1); chronic myelogenous leukemia (1).
A further 46 diseases each share a sentence with MDM4 in 1 paper.